LCAT (lecithin-cholesterol acyltransferase)
Diseases named in the same sentence as LCAT in open-access papers (continued):
Sharing a sentence is not in itself a finding about the gene and the disease.
tumor (continued). "The results indicated that the decrease of LCAT will lower the level of lysoPC (16:0) and promote tumor metastasis in different ways." (PMID 36428687, 2022). "Subsequently, we constructed a risk model based on four LMAGs—LCAT, MED22, MED7, and TXNRD1—which presented noteworthy prognostic values and was closely associated with tumor grade, tumor stage, and T-staging." (PMID 36330335, 2022). "RPS6KA6 and LCAT were found to be correlated with T (P = 0.015; P = 0.042), and LCAT was significantly related to new tumor events (P = 0.028)." (PMID 34034705, 2021). "Increased oxCEs in the tumor-adjacent-normal tissue suggest that increased LCAT-catalyzed production of lysoPCs has occurred in these tissues." (PMID 34707244, 2021). "A significantly low DNA methylation were noted for SPP1 relative to high expression levels in tumor tissues, while high DNA methylation and low expression for LCAT (P < 0.0001)." (PMID 32514252, 2020). "SPP1 exhibited significantly higher expression in tumor samples than in adjacent normal samples, whereas LCAT exhibited significantly decreased expression in tumor samples (P < 0.0001)." (PMID 31695766, 2019). "In particular, UBAP2L was markedly and highly expressed in T2 tumours (72.5 % vs. 27.5 %) and LCAT was lowly expressed in T2 tumours (30.0 % vs. 70.0 %) and highly expressed in T1 tumours (72.6 % vs. 27.4 %)." (PMID 27567667, 2016). "Identifying m6A modification sites on LCAT mRNA may help develop targeted therapies that alter RNA structure, thereby enhancing the anti-tumor effects of existing therapies." (PMID 40003919, 2025). "These correlations are crucial, suggesting that LCAT may influence anti-tumor immunity by modulating immune regulatory factors." (PMID 40003919, 2025). "In ACC and COAD, LCAT expression levels significantly affect tumor progression." (PMID 40003919, 2025). "This duality underscores the importance of context-specific mechanisms, where LCAT may either promote or inhibit tumor progression depending on the tumor microenvironment and genetic background." (PMID 40003919, 2025). "In addition, in ACC and COAD tumors, LCAT is likely to promote tumor progression by regulating cell cycle checkpoints." (PMID 40003919, 2025). "In contrast, in ACC and COAD, LCAT may promote tumor progression by enhancing DNA replication and cytokine–cytokine receptor interactions, which are essential for tumor cell proliferation and survival." (PMID 40003919, 2025). "In addition, in ACC and COAD tumors, LCAT is likely to promote tumor progression through cytokine–cytokine receptor interaction." (PMID 40003919, 2025). "The GO enrichment analysis of the LCAT high and low expression groups in ACC and COAD suggests that LCAT may promote tumor progression in ACC and COAD by affecting DNA replication and immune responses." (PMID 40003919, 2025). "Additionally, we also looked at the potential of LCAT as a predictive biomarker of immunotherapy response and its connection to the immune response in the tumor microenvironment." (PMID 40003919, 2025). "These insights suggest that future research should investigate whether demethylating drugs can enhance LCAT expression, potentially restoring its tumor-suppressing function." (PMID 40003919, 2025). "This aligns with previous studies showing that LCAT inhibits tumor progression by modulating cholesterol metabolism and enhancing HDL functionality, which may suppress tumor growth and immune evasion." (PMID 40003919, 2025). "Furthermore, LCAT was found to be correlated with T stage and new tumor events, and RPS6KA6 was found to be correlated with T stage." (PMID 34034705, 2021). "Finally, LCAT was found to be correlated with T stage and new tumor events, and RPS6KA6 was found to be related to T stage." (PMID 34034705, 2021). "LCAT exhibited significantly decreased expression in tumor tissues (P < 0.0001)." (PMID 31695766, 2019).
tumor (continued). "For instance, modulating lipid metabolic pathways with existing inhibitors targeting LPCAT1 or ACSL4 may disrupt aberrant lipid flux within tumor cells, impeding tumor growth and overcoming chemoresistance, while LCAT inhibitors could impair membrane integrity and energy homeostasis in HCC cells." (PMID 40500772, 2025). "In ACC and COAD, LCAT may promote tumor growth, while in LGG and LIHC, it may inhibit progression." (PMID 40003919, 2025). "Additionally, HDL-C synergizes with lenvatinib to enhance anti-tumor efficacy, suggesting that targeting the LCAT/HDL-C axis could improve immunotherapy and treatment outcomes in HCC." (PMID 40438106, 2025). "Therefore, it is speculated that the drugs xanthohumol and dapsone may affect tumor progression by affecting the abnormally expression of LCAT and NAT2, respectively." (PMID 36353119, 2022). "Thus, dapsone and xanthohumol may alter the tumor progression of high risk COAD patients by acting on NAT2 and LCAT, respectively." (PMID 36353119, 2022). "In addition, LCAT was highly expressed in stage I tumours (71.2 % vs. 28.8 %)." (PMID 27567667, 2016). "To further understand the prognostic value of LCAT in different tumors, we analyzed the correlation between LCAT expression and OS, DSS, and PFI in tumor patients using univariate Cox regression analysis." (PMID 40003919, 2025). "Next, we systematically explored the relationship between the expression of 37 common DEGs in tumor tissues and OS rate in TCGA and constructed a novel prognosis-related model composed of five genes (AURKA, PZP, RACGAP1, ACOT12 and LCAT)." (PMID 34336648, 2021). "The KEGG enrichment analysis further supports this view, showing that LCAT may promote ACC tumor progression through the IL-17 signaling pathway and promote COAD tumor progression through complement and coagulation cascades." (PMID 40003919, 2025). "Complement and coagulation cascades may be regulated by LCAT in LGG and LIHC, explaining the common mechanism of action of LCAT in inhibiting tumor progression." (PMID 40003919, 2025). "The Reactome enrichment analysis further emphasizes the role of LCAT in regulating peptide chain elongation and complement cascades, which may be key molecular mechanisms for its inhibitory effect on LGG and LIHC tumor progression." (PMID 40003919, 2025). "In BLCA, LIHC, LUAD, and THCA, there is no big distinction regarding LCAT methylation between normal and tumor tissues." (PMID 40003919, 2025). "Subsequently, we will develop a sensitive technique to detect the presence of SPP1 and LCAT in cell-free circulating tumor DNA (ctDNA), which will not only benefit patients who undergo surgery but will also help to screen patients with HCC." (PMID 31695766, 2019). "Finally, we analyzed the expression differences of LCAT in HCC patient tumor tissues and adjacent nontumor tissues in TCGA." (PMID 38195525, 2024). "Next, we systematically explored the relationship between the expression of 37 common DEGs in tumor tissues and overall survival (OS) rate of HCC patients in TCGA and constructed a novel prognostic model composed of five genes (AURKA, PZP, RACGAP1, ACOT12 and LCAT)." (PMID 34336648, 2021). "Unlike ACC and COAD, LCAT may play a role in inhibiting tumor progression in LGG and LIHC." (PMID 40003919, 2025).
renal disease (18 papers, 2016 to 2025). "While the association between reduced LCAT activity and renal disease is well-established, our study introduces a novel perspective by linking LCAT activity to adverse outcomes across the entire CKD spectrum." (PMID 39154733, 2024). "For examples, both clinical and experimental evidence has showed that defective HDLs caused by ATP-binding cassette transporter type A1 and lecithin–cholesteryl acyltransferase (LCAT) deficiencies are underlying contributory factors for renal diseases." (PMID 34692787, 2021). "This review summarizes the main alterations of HDL in CKD, focusing on the latest update of acquired and genetic LCAT defects associated with the progression of renal disease." (PMID 33807271, 2021). "Plasma lipoprotein alterations have been related to renal disease; and, indeed, renal disease can reoccur in LCAT deficient cases who underwent kidney transplantation, thus supporting the systemic cause of the renal damage." (PMID 32708515, 2020). "Two of the three cases are siblings, but only one developed renal disease, although they had the same LCAT genotype and the same LCAT activity, which suggests that renal disease is not only dependent on LCAT deficiency." (PMID 31684177, 2019). "We used multivariate regression analyses to test whether markers of LCAT activity or altered lipid metabolism were associated with the prevalence of severe renal disease (CKD stage III–V/ESRD) in FLD patients." (PMID 35065092, 2022). "The interconnection between HDL and renal function is confirmed by the fact that genetic HDL defects can lead to kidney disease; in fact, mutations in apoA-I, apoE, apoL, and lecithin–cholesterol acyltransferase (LCAT) are associated with the development of renal damage." (PMID 33807271, 2021). "Renal disease is not only dependent on LCAT deficiency, and could be due to the presence of VLDL particles, which are rich in triglycerides, free cholesterol and LpX." (PMID 31684177, 2019). "Furthermore, although biomarkers of LCAT deficiency have been identified, their suitability to monitor disease progression and therapeutic efficacy is unclear, as little data exist on the rate of progression of renal disease." (PMID 35065092, 2022). "Monitoring the effect of recombinant LCAT on LpX levels could provide an early indicator of the effectiveness of the therapy, but it still is not known whether LpX is causally involved or simply associated with the renal disease." (PMID 26919698, 2016). "Genetic LCAT deficiency is the most emblematic case and represents a unique tool to evaluate the impact of alterations in the HDL system on the progression of renal disease." (PMID 33807271, 2021). "In conclusion, this is the first study that prospectively addresses the impact of plasma LCAT levels in predicting renal disease onset and progression." (PMID 32708515, 2020). "This review provides the first step toward the identification of disease biomarkers to be used in clinical trials and suggests that restoring LCAT activity to subnormal levels may be sufficient to prevent renal disease progression." (PMID 35065092, 2022). "This knowledge may help to design more drug-like chemicals to ‘boost’ the activity of LCAT and prevent heart and kidney disease, especially in people who carry a defective version of the enzyme." (PMID 30479275, 2018). "It seems obvious that the LCAT genotype, which mostly determines the activity of the LCAT enzyme, is not uniquely responsible for renal disease in patients." (PMID 31684177, 2019). "Further development of recombinant LCAT for the treatment of FLD will likely depend on the use of biomarkers, because of the rarity of the disease and the long time period that is necessary for renal disease to develop." (PMID 26919698, 2016).
renal disease (continued). "Renal disease patients show significantly reduced plasma HDL-C, APOA-I, serum PON1 protein concentration, PON1 arylesterase/ paraoxonase activity, and LCAT activity, indicating the impaired interactions of PON1 with APOAI and LCAT in dysfunctional HDL in these patients." (PMID 39594433, 2024). "Finally, the absence of renal disease in FED is presumably prevented by the residual LCAT activity and the lack of formation of a significant amount of LpX." (PMID 33807271, 2021). "The deposition and accumulation of nephrotoxic and pro-inflammatory lipoprotein X (Lp-X) particles, mainly in the mesangium, in the absence of LCAT, may explain the development of renal disease." (PMID 34256778, 2021). "However, in our study, the change in LCAT activity along the progress of kidney disease was not significant." (PMID 30857306, 2019). "Even a relatively small increase in activity could potentially slow or reverse the progression of renal disease in some FLD patients because FED patients with only partial LCAT activity do not develop renal disease." (PMID 30479275, 2018). "In summary, we have shown that LpX is remodeled by LCAT and apoA-I and that LpX alone is sufficient to induce many of the renal pathologic features seen in FLD renal disease, and hence may be a suitable biomarker for monitoring the response to any new therapy for FLD, such as recombinant LCAT." (PMID 26919698, 2016).
infection (9 papers, 2014 to 2025). The state of being infected such as from the introduction of a foreign agent such as serum, vaccine, antigenic substance or organism. "Additionally, LCAT deficiency is associated with abnormal lipid deposition in the kidneys, leading to renal dysfunction, which may further exacerbate the host immune and inflammatory response during infection." (PMID 40853910, 2025). "Somewhat similar findings were shown in other studies, where LCAT activities were reduced during infection." (PMID 35071235, 2021). "Previous studies also discovered that LCAT was down‐regulated in COVID‐19 patients and may be predictive of non‐survival in the patients, due to the impaired liver function related with infection." (PMID 38403992, 2024). "Interestingly, female worm maturation occurs between 22 and 28 days post-infection, during which the expression level of LCAT continues to increase in female worms, while it decreases in male worms." (PMID 38720339, 2024). "Indeed, our intravenous infection study showed significantly enhanced PSM-mediated mortality in LCAT−/− mice compared to WT mice, clearly showing protection by HDL against staphylococcal PSMs in this model." (PMID 34321507, 2021). "Lecithin-cholesterol acyltransferase (LCAT) was originally described in Plasmodium berghei as a phospholipase named PL in a screen to identify sporozoite proteins involved in the establishment of the infection." (PMID 29507893, 2018). "Intravenous infection of WT and LCAT−/− mice with MRSA led to significant increased mortality in the LCAT−/− mice." (PMID 34321507, 2021).
metabolic disorders (6 papers, 2012 to 2025). "Based on these observations, future research could investigate the role of LCAT in the occurrence of metabolic disorders causing MetS." (PMID 37510094, 2023). "The cases of LCAT and apoA1 deficiencies demonstrate the diverse phenotypic spectrum of HDL-C-related metabolic disorders, highlighting how early genetic screening can guide clinical management and follow-up strategies." (PMID 40476138, 2025).
genetic disease (5 papers, 2007 to 2023). "Arg244 is a position commonly mutated in LCAT genetic disease (R244G, R244H, R244C, and R244L) and its side chain forms unique interactions in the observed active and inactive states of LCAT." (PMID 30479275, 2018). "Primary causes for low HDL cholesterol include genetic disorders due to mutations in the ATP-binding cassette transporter A1, apolipoprotein A-I, and lecithin-cholesterol acyltransferase (LCAT)." (PMID 27579193, 2016). "Actually, in order to gain new insights into how a phospholipase engages its physiological target and genetic disease influences the interface, a direct visualization of LCAT bound to HDL complexes is needed." (PMID 36588724, 2022).
kidney (1 paper, 2024). "Synthetic LP-X, which was designed to match the lipid composition of endogenous LP-X, is a multilamellar vesicle that, like endogenous LP-X, has cathodal migration on agarose gel electrophoresis and, when administered to LCAT-deficient mice, induces kidney injury." (PMID 38338310, 2024).
psychiatric disorder (1 paper, 2025). A disorder characterized by behavioral and/or psychological abnormalities, often accompanied by physical symptoms. "Concurrently, LPCs derived from PC breakdown or lipoproteins, have also shown perturbed levels in various psychiatric disorders, likely influenced by enzymatic processes such as lecithin-cholesterol acyltransferase (LCAT) and phospholipase A." (PMID 40634860, 2025).
LCAT also shares sentences with these, for which no sentence is quoted: bipolar disorder (3 papers); end-stage renal disease (3); Hodgkins lymphoma (3); age-related macular degeneration (2); breast invasive carcinoma (2); focal glomerulosclerosis (2); acquired lipodystrophy (1); acute coronary syndrome (1); acute myocardial infarction (1); Adrenal insufficiency (1); alcoholic liver diseases (1); angiokeratoma (1); babesiosis (1); bacteremia (1); bacterial infections (1); Bietti crystalline dystrophy (1); cardiomyopathies (1); cataract (1); central nervous system diseases (1); cervical cancer (1); cervical squamous cell carcinoma (1); cholesterol ester storage disease (1); corneal diseases (1); cystinosis (1); diffuse large B-cell lymphoma (1); End Stage Liver Disease (1); endocervical adenocarcinoma (1); epilepsy (1); esophageal carcinoma (1); falciparum malaria (1).
A further 56 diseases each share a sentence with LCAT in 1 paper.